INS (insulin)
Diseases named in the same sentence as INS in open-access papers (continued):
Sharing a sentence is not in itself a finding about the gene and the disease.
benign breast tumor (1 paper, 2018). "Administration of BV juice showed controlling effects on HOMA related indices, consequently might have beneficial effects on insulin signaling-related functions in women with benign breast tumor." (PMID 29796035, 2018).
bipolar I disorder (1 paper, 2025). A bipolar disorder that is characterized by at least one manic or mixed episode. "Here, we show that bipolar I disorder (BDI)-patient-induced pluripotent stem cell (iPSC)-derived islet-like organoids exhibited Syt7-dependent insulin secretion defects; moreover, Syt7-deficiency-induced insulin hyposecretion generated depression-like behaviors in Syt7 KO mice in the light phase." (PMID 40330888, 2025).
bleeding (1 paper, 2025). "While SGLT2Is were associated with lower variceal bleeding and HE, the insulin group had higher baseline MELD scores." (PMID 40429923, 2025).
bronchopneumonia (1 paper, 2010). Acute inflammation of the walls of the terminal bronchioles that spreads into the peribronchial alveoli and alveolar ducts. "They showed good clinical evolution after fluid replacement and the administration of insulin, although one of the patients developed bronchopneumonia and needed intubation and mechanical ventilation." (PMID 20682062, 2010).
carcinoma in situ (1 paper, 2023). "In addition, exercise might prevent the transformation of carcinoma in situ through lowering blood glucose and improving insulin sensitivity." (PMID 37958310, 2023).
cerebellar degeneration (1 paper, 2025). Degeneration of the cerebellum. "However, the overall effects of AUD on insulin/IGF signaling networks in the cerebellum were modest compared with previous findings in experimental models suggesting that other factors contribute to cerebellar degeneration in humans with AUD." (PMID 41255373, 2025).
cerebral (1 paper, 2012). "With SNS activation, insulin secretion from the beta cells is suppressed, and the insulin-dependent glucose uptake via GLUT4 into the body periphery becomes limited, referred to as “cerebral insulin suppression” (CIS)." (PMID 22655178, 2012).
cerebral microbleeds (1 paper, 2020). Cerebral microbleeds are a group of pathological processes affecting the small arteries, arterioles, capillaries and venules of the brain, as detected by brain imaging techniques. "In logistic regression analysis an independent association was found between lowest quartile of CCA/MISS and higher insulin dose: OR per 1 IU/kg 5.38 (95 % CI 1.38–21.04), p = 0.016, as well as with the presence of more than two cerebral microbleeds vs. zero: OR 12.00 (2.85–50.65), p = 0.001." (PMID 32063882, 2020).
Charcot-Marie-Tooth disease (1 paper, 2021). An inherited degenerative disorder involving the peripheral nerves. "However, this same mouse model has been used as a model of Charcot Marie Tooth disease, where higher serum insulin was reported in Dhtkd1 -/- mice compared with WT in both the fasted and re-fed state." (PMID 34484123, 2021).
Charcot-Marie-Tooth neuropathy (1 paper, 2022). "Nevertheless, OADH/DHTKD1 are linked to impaired insulin sensitivity, cardiovascular disease risks, and Charcot-Marie-Tooth neuropathy." (PMID 35721081, 2022).
CHARGE syndrome (1 paper, 2022). CHARGE syndrome is a multiple congenital anomaly syndrome characterized by the variable combination of multiple anomalies, mainly Coloboma; Choanal atresia/stenosis; Cranial nerve dysfunction; Characteristic ear anomalies (known as the major 4 C's). "Interestingly, while both models exhibited defects in line with patient data, we identified previously unreported features for CHARGE syndrome, including reduced levels of insulin, which could potentially be tested as a new biomarker for CHARGE syndrome." (PMID 36232804, 2022).
child (1 paper, 2017). "In child cancer survivors, few studies have evaluated the role of these adipokines, in addition to levels of insulin, adiposity and the presence of MS." (PMID 28193268, 2017).
choledocholithiasis (1 paper, 2025). Presence or formation of gallstones in the common bile duct. "It has been suggested that MS may be related to the pathophysiology of choledocholithiasis, possibly due to factors such as insulin resistance, altered bile composition, and increased biliary cholesterol." (PMID 40709109, 2025).
Chuvash polycythemia (1 paper, 2025). Chuvash erythrocytosis is a rare, genetic, congenital secondary polycythemia disorder characterized by increased hemoglobin, hematocrit and erythropoietin serum levels and normal oxygen affinity, which usually manifests with headache, dizziness, dyspnea and/or plethora. "Experimental long-term interventions as applied to mice are hardly doable in humans, but pertinent changes in glycemia and insulin sensitivity have been described in association with hematocrit changes caused by altitude, Chuvash polycythemia, and therapeutic administration of rhEPO or testosterone." (PMID 40238885, 2025).
Chylothorax (1 paper, 2024). The presence of chyle in the thoracic cavity. "It is important to consider the role insulin resistance may play in the pathogenesis of chylothorax due to its effect on increased chylomicron production and increased extravasation of lymphatic fluid." (PMID 39119374, 2024). "This case suggests that metabolic optimization to decrease insulin resistance, improve chylomicron metabolism, decrease lymphatic permeability, and lower serum triglycerides, as occurs with a ketogenic diet, should be considered for conservative treatment of chylothorax and warrants further study." (PMID 39119374, 2024). "The increased chyle production due to insulin resistance was likely not the only contributing factor to her persistent chylothorax." (PMID 39119374, 2024).
citrin deficiency (1 paper, 2022). "Intriguingly, in children with citrin deficiency, oral pyruvate induces significant enhancements of fasting insulin levels for months." (PMID 35991638, 2022).
clear cell carcinoma (1 paper, 2013). "Alcohol, in general, has been reported to reduce cellular proliferation by influencing the insulin and insulin-like growth factor (IGF) pathways, and these pathways have been implicated in the early development and prognosis of clear cell carcinoma types." (PMID 23339562, 2013).
Clear cell ovarian carcinomas (1 paper, 2013). "Clear cell ovarian carcinomas share similar features with clear cell renal cell carcinomas and it has been suggested that moderate alcohol intake may improve insulin sensitivity and regulate related pathways that are implicated in the etiology of these carcinomas." (PMID 23339562, 2013).
cocaine abuse (1 paper, 2016). Disorders related or resulting from use of cocaine. "We describe an interesting case of euglycemic DKA in a middle-aged diabetic female presenting with elevated anion gap metabolic acidosis, with near-normal blood glucose, in the settings of noncompliance to insulin and cocaine abuse." (PMID 27579186, 2016).
colon adenomatous polyps (1 paper, 2018). "In addition, the possible protective effect of metformin or the increased risk of insulin on colon adenomatous polyps remains very controversial." (PMID 30157768, 2018). "For example, metformin has been reported to decrease colon adenomatous polyps while insulin therapy may increase them." (PMID 30157768, 2018).
colorectal adenocarcinoma (1 paper, 2021). The most common type of colorectal carcinoma. "Then the R8-CM-β-CD formed an inclusion complex with the insulin and was evaluated for intestinal absorption of insulin using an immortalised cell line of human colorectal adenocarcinoma (Caco-2) cell monolayer in vitro and diabetic rats in vivo." (PMID 34072062, 2021).
congenital hydronephrosis (1 paper, 2023). Congenital hydronephrosis is a renal urinary disease characterized by distension and dilation of the renal pelvis and calyces secondary to various congenital obstructive malformations of the kidneys and urinary tract that can evolve to renal atrophy. "Only children with congenital hydronephrosis were found to have a significantly decreased risk (RR 0.57, 95% CI 0.35–0.92) of receiving > 1 prescription for insulin/insulin analogues aged 0 to 9 years." (PMID 36869270, 2023). "It should be confirmed in other data sources before children with congenital hydronephrosis are considered to truly have a decreased risk of requiring insulin therapy." (PMID 36869270, 2023). "The decreased risk of receiving > 1 prescription for insulin/insulin analogues among those with congenital hydronephrosis has not previously been reported and may be a chance finding due to the number of comparisons made." (PMID 36869270, 2023).
cryptococcal infections (1 paper, 2022). "Here, we showed that defects in C. elegans insulin/insulin-like growth factor-1 (IGF-1) signaling (IIS) pathway influenced animal lifespan and mechanisms of host resistance in cryptococcal infections, which required the activation of aging regulator DAF-16/Forkhead box O transcription factor." (PMID 35733100, 2022).
demyelinating disorders (1 paper, 2021). "Despite insulin’s ability to promote OL survival, treatment with insulin appears to be ineffective in demyelinating disorders." (PMID 33669242, 2021).
dendritic cell neoplasms (1 paper, 2025). "The enriched pathways included insulin resistance and blast plasmacytoid dendritic cell neoplasms." (PMID 40969325, 2025).
diabetic angiopathy (1 paper, 2022). "Given the effects of the curcuminoid in reducing vascular oxidative stress, the pathways involved in the protection against oxidative stress and glycation were investigated in adipose tissue, liver (insulin sensitive), kidney and heart (tissues affected by the diabetic angiopathy)." (PMID 35628465, 2022).
disorder of sexual differentiation (1 paper, 2024). A congenital disorder characterized by abnormalities in the development of the sexual characteristics. "Interestingly, a few patients with Disorders of Sexual Differentiation (DSD) shared rare pathogenic variants in the SRD5A2, HSD17B3 and HSD3B2 while patients with Glucose and Insulin Homeostasis carried theirs in GCK and HNF1A genes." (PMID 38637882, 2024).
ductal carcinoma in situ (1 paper, 2025). "Insulin-treated patients demonstrated a lower prevalence of pTNM stage I cancers but a nearly fivefold increase in ductal carcinoma in situ (DCIS)." (PMID 40764810, 2025). "In the subgroup treated with insulin (n = 160), patients showed a significantly lower incidence of pTNM stage I tumors (15.0% vs. 30.5%; p < 0.001) and a markedly higher rate of ductal carcinoma in situ (DCIS) (10.0% vs. 2.3%; p < 0.001)." (PMID 40764810, 2025).
dystocia (1 paper, 2024). Slow or difficult obstetric labor or childbirth. "Overall, these studies shed light on the intricate associations between GH genotypes and various phenotypic traits, including size, insulin levels, carcass traits, fertility, and dystocia." (PMID 39095829, 2024).
early-onset epilepsy (1 paper, 2023). "Syndromes characterized by neonatal-onset diabetes and early-onset epilepsy are described (mutations in GCK, INS, KCNJ11, and ABCC8)." (PMID 37048663, 2023).
emotional instability (1 paper, 2025). "Such fluctuations in glucose homeostasis are known to influence the secretion of neuroendocrine regulators, including insulin and cortisol, thereby exacerbating emotional instability." (PMID 41346670, 2025).
encephalomalacia (1 paper, 2023). Localized atrophy of the brain parenchyma due to aging, hemorrhage, infarct, or inflammation. "In this case report, we present our experience in the treatment of the infant, switching from insulin to oral SUs and we thought that SUs have limited effects on improving the prognosis of neurodevelopmental disturbances in NDM with foci of encephalomalacia." (PMID 36937531, 2023).
Epileptic encephalopathy (1 paper, 2019). A condition in which epileptiform abnormalities are believed to contribute to the progressive disturbance in cerebral function. "Diseases associated with synaptic vesicle cycle defects include early infantile epileptic encephalopathy and defects in insulin secretion including defects in degradation of gangliosides which are abundantly expressed in the nervous system." (PMID 31323913, 2019).
erythroleukemia (1 paper, 2023). Acute erythroid leukemia characterised by the presence of at least 50% erythroid precursors and at least 20% myeloblasts in the bone marrow. "Here, the interplay between the lipolytic release and intercellular transfer of GPI-APs and its potential functional impact was studied using transwell co-culture with human adipocytes as insulin-/SU-responsive donor cells and GPI-deficient erythroleukemia as acceptor cells (ELCs)." (PMID 36902257, 2023).
familial cancers (1 paper, 2023). "It is also possible that this treatment could be applied to other types of cancers, including various familial cancers that are dependent on the insulin-regulated PI3K-Akt-mTOR pathway, and could represent the first effective prevention method that does not have adverse effects." (PMID 37679316, 2023).
Fibroadenoma (1 paper, 2021). A benign tumor of the breast characterized by the presence of stromal and epithelial elements. "Evidence also suggest an elevated expression of RHEB in epithelial cells of fibroadenomas providing an association of RHEB with insulin/AKT/TOR signaling pathway in benign tumor development." (PMID 33593445, 2021).
Flavivirus Infections (1 paper, 2022). Infections with viruses of the genus FLAVIVIRUS, family FLAVIVIRIDAE. "These analyses reinforce the value of in vivo analyses that examine the role of glucose and insulin in the flavivirus infection of vector mosquitoes." (PMID 35458395, 2022).
follicular thyroid cancer (1 paper, 2012). "In a study using human follicular thyroid cancer cell line FTC-133, insulin glargine displayed similar mitogenic potency in comparison with human insulin." (PMID 23284776, 2012).
gastric NETs (1 paper, 2021). "A systematic review and meta-analysis showed that DM was a significant risk factor in development of pancreatic and gastric NETs among all case–control studies examined, and the overall risk was greater in patients with DM who were receiving insulin." (PMID 34046189, 2021).
gastrointestinal infection (1 paper, 2025). "The patient was treated for a hyperosmolar hyperglycemic state precipitated by gastrointestinal infection with intravenous fluids, antibiotics, and insulin therapy." (PMID 41321884, 2025).
gastrointestinal neuroendocrine tumor (1 paper, 2022). "Diarrhea and flushing were reported by 62 patients (91.1%), one patient (1.5%) had an adrenocorticotropic hormone (ACTH)-producing gastrointestinal neuroendocrine tumor, and five (7.4%) had insulin-producing disease." (PMID 36551507, 2022).
glomerulonephritis (1 paper, 2021). A renal disorder characterized by damage in the glomeruli. "Attenuation of growth hormone action in mice at a mature adult age (6‐months) extends lifespan, reduces protein oxidation and glomerulonephritis in females while improving insulin sensitivity and decreasing lipid peroxidation, glomerulonephritis, and neoplasms in males." (PMID 34811874, 2021).
glycogen storage disease type Ia (1 paper, 2008).
GM1 gangliosidosis (1 paper, 2020). A rare lysosomal storage disorder characterized biochemically by deficient beta-galactosidase activity and clinically by a wide range of variable neurovisceral, ophthalmological and dysmorphic features. "Importantly, in terms of further development of ICV-ERT for GM1 gangliosidosis, we show here that purified rhβ-gal exhibits pH-dependent and concentration-dependent dynamic self-association, a property that has also been observed for insulin." (PMID 31481471, 2020).
Granuloma (1 paper, 2021). A compact, organized collection of mature mononuclear phagocytes, which may be but is not necessarily accompanied by accessory features such as necrosis. "Reports of T2D patients developing a TB granuloma at the site of insulin injection suggests that insulin may contribute to TB reactivation." (PMID 34835407, 2021).
hand eczema (1 paper, 2025). A form of contact dermatitis characterised by inflammation, redness and itching of the hands. "The distribution of lesions reported in addition to concurrent hand eczema included the following: the face (5/13), trunk (3/13), forearms/arms (3/13), flexural surfaces (3/13), feet (2/13), lips (1/13), and insulin pump infusion site (1/13)." (PMID 40008983, 2025).
hemangiopericytoma (1 paper, 2015). An antiquated term that refers to benign or malignant mesenchymal neoplasms characterized by the presence of neoplastic spindle-shaped to round cells arranged around thin-walled branching vascular spaces. "It is of note that insulin-independent hypoglycemia was induced by sorafenib in a patient with hemangiopericytoma and was responsive to glucocorticoid treatment." (PMID 26354794, 2015).
hemolysis (1 paper, 2020). Disruption of the integrity of the erythrocyte membrane causing release of hemoglobin. "Notably, there was hemolysis at the 0 and 30-minute time points, which may have spuriously lowered insulin levels in these samples." (PMID 33210059, 2020).
hereditary multiple exostoses (1 paper, 2014). An exostosis that has_material_basis_in a mutation on the genes EXT1, EXT2 and EXT3 which results_in multiple bony spurs throughout a child's growth. "We hypothesized that loss of function of EXT1 or EXT2 in subjects with hereditary multiple exostoses (HME) affects pancreatic insulin secretion capacity and development." (PMID 25541963, 2014).
heroin addiction (1 paper, 2017). "Furthermore, rs1137070 and heroin addiction interactively contributed to GMV alterations in the OFC, TPO, ACC, and INS.R." (PMID 28345608, 2017).
HIV encephalitis (1 paper, 2014). "Our results support accumulating evidence that rabies as well as many other CNS pathologies (e.g. Alzheimer's, Huntington's, HIV encephalitis) can be considered metabolic diseases as they result in progressive impairment of the brain's capacity to utilize glucose and/or insulin." (PMID 24763072, 2014).
hyperamylasemia (1 paper, 2024). Abnormally high level of amylase in the blood. "Additionally, though we found hyperamylasemia and hyperlipasemia after hepatectomy for living liver donors, we have not yet clarified the involvement of pancreatic hormones such as glucagon and insulin." (PMID 38514681, 2024).
Hyperhomocystinemia (1 paper, 2021). An increased concentration of homocystine in the blood. "Hyperhomocystinemia also plays a harmful role in pancreatic β‐cell metabolism and insulin secretion." (PMID 33841822, 2021).
hypermobility syndrome (1 paper, 2011). "In patients with hypermobility syndrome (including several cases of DDH), growth hormone, insulin, and IGF-1 levels were elevated, leading us to endocrine abnormalities in DDH." (PMID 24977057, 2011).
hypertensive nephropathy (1 paper, 2025). Kidney damage that results from chronically elevated blood pressure; complications include glomerular damage resulting in proteinuria and hematuria. "A ceRNA regulatory network directly associated with hypertensive nephropathy was established, and the insulin signaling pathway was identified as directly linked to hypertensive nephropathy, modulated by lncRNAs SNHG14, TUG1, ZNF252P-AS1, and MIR503HG." (PMID 40083322, 2025).